SALL1 (spalt like transcription factor 1)
Diseases named in the same sentence as SALL1 in open-access papers (continued):
Sharing a sentence is not in itself a finding about the gene and the disease.
cancer (11 papers, 2018 to 2026). A tumor composed of atypical neoplastic, often pleomorphic cells that invade other tissues. "In this review, we focus on Sall1 as it is has been more frequently studied in the context of cancer as compared to the other Sall proteins." (PMID 34195082, 2021). "SALL4 is a well-recognized oncogene; however, SALL1–3 play dual roles depending on the cancer context and stage of the disease." (PMID 34944911, 2021). "It has been shown that the SALL1 promoter was methylated in breast and other epithelial cancers, but little is known about the role of SALL1 in the pathogenesis of human cancers." (PMID 29625565, 2018). "Expression of KLF4 and SALL1 in cancer suppression and carcinogenesis." (PMID 34195082, 2021). "In addition, Sall1 is affecting the progression of cancer through the upregulation of the epithelial marker E-cadherin and downregulation of the mesenchymal markers vimentin and N-cadherin, driving mesenchymal-to-epithelial transition." (PMID 34195082, 2021). "Most of the studies have focused on the functional relationship of NuRD with SALL1 or SALL4 in development and cancer." (PMID 34944911, 2021). "SALL1 transfection in MCF-7, MDA and E0771 cells significantly induced cancer cells to arrest in S phase and decrease in G0/G1 phase." (PMID 29625565, 2018). "Over-expression of SALL1 significantly induced active, phosphorylated ATM in MCF-7, MDA and E0771 cancer cells." (PMID 29625565, 2018). "SALL1, SALL2, and SALL4 cancer-related isoforms have been reported." (PMID 34944911, 2021). "However, the function of SALL1 in cancer development has not been determined." (PMID 33441805, 2021).
infection (10 papers, 2009 to 2026). The state of being infected such as from the introduction of a foreign agent such as serum, vaccine, antigenic substance or organism. "Expression of Tgfbr1, Hexb, Golm1, and Sall1 increase with microglia maturity, and maturation is dependent on TGF-β signaling which was up-regulated by maternal infection." (PMID 38730262, 2024).
kidney disease (4 papers, 2023 to 2025). "Further studies reveal that in individuals undergoing broad-based genetic testing with a kidney gene panel, variants in SALL1 are rare, yielding a prevalence of 1:1,592 among patients tested for monogenic kidney disease." (PMID 40989825, 2025). "SALL1 variants have also been reported in patients with isolated kidney disease, highlighting the wide variability in the expression of SALL1-associated phenotypes." (PMID 40348827, 2025). "The other had partial fragment deletion of SALL1 (del6Mb), which resulted deletion of other genes related to kidney disease." (PMID 37644569, 2023).
kidney (2 papers, 2015 to 2022). "Three novel missense variants which were absent in Gnomad were identified in PAX2 (p.Ser305Leu in child with unilateral hypodysplastic kidney), SALL1 (p.Phe447Tyr in patient with bilateral VUR) and RET genes (p.Gly533Ser in child with unilateral vesico-ureteric junction obstruction)." (PMID 34979951, 2022).
neurodegenerative disease (2 papers, 2022 to 2023). A disorder of the central nervous system characterized by gradual and progressive loss of neural tissue and neurologic function. "The finding that haploinsufficiency for Sall1 is associated with substantial changes in the expression of genes associated with aging and neurodegenerative diseases raises the possibility that quantitative changes in its expression could contribute to disease phenotypes." (PMID 37322178, 2023).
cardiac disease (1 paper, 2023). "Altogether, these findings suggest that patients with SALL1 deletions show a milder phenotype, since they are less likely to fulfil the three major diagnostic criteria and have a lower frequency of renal and cardiac disease." (PMID 36833185, 2023).
neurological diseases (1 paper, 2025). "For instance, key microglial homeostatic signature genes such as P2RY12 and spalt-like transcription factor 1 (SALL1) are implicated in neurological diseases, and their study will benefit from systems in which they are highly expressed at baseline." (PMID 40231345, 2025).
SALL1 also shares sentences with these, for which no sentence is quoted: malaria (7 papers); Duane-radial ray syndrome (6); salmonellosis (4); Baraitser-Winter syndrome (3); auricular malformation (2); bacterial infection (2); BOR syndrome (2); branchio-oto-renal syndrome (2); colorectal cancer (2); congenital malformation syndrome (2); kidney failure (2); retinoblastoma (2); Salmonella Infections (2); staphylococcal infection (2); Tetralogy of Fallot (2); type 2 diabetes (2); Alzheimer disease (1); arthrogryposis (1); autism (1); bladder cancer (1); branchiootic syndrome 1 (1); celiac disease (1); chronic lymphocytic leukemia (1); ciliopathies (1); coloboma (1); Colorectal tumour (1); congenital heart disease (1); coronary atherosclerosis (1); cortical blindness (1); Duane retraction syndrome (1).
A further 49 diseases each share a sentence with SALL1 in 1 paper.